CD34 (CD34 molecule)
Diseases named in the same sentence as CD34 in open-access papers (continued):
Sharing a sentence is not in itself a finding about the gene and the disease.
serous ovarian cancer (2 papers, 2019 to 2026). "A novel high‐grade serous ovarian cancer organoid system was developed from patient samples, preserving the native immune microenvironment and vascular components (CD34+ endothelial cells)." (PMID 41503026, 2026). "Here, we used immunohistochemical (IHC) staining and 7-color multiplex staining to evaluate CD8 (cluster of differentiation 8), CD68, PD-L1 (programmed death-ligand 1), CD34, FAP (fibroblast activation protein), and cytokeratin in 220 tissue cores from 26 high-grade serous ovarian cancer samples." (PMID 31772388, 2019).
spinal muscular atrophy (2 papers, 2011 to 2025). A motor neuron disease that affect the muscles, and characterized by muscle weakness and atrophy resulting from progressive degeneration and irreversible loss of the anterior horn cells in the spinal cord (i.e., lower motor neurons) and the brain stem nuclei. "Immunohistochemical diagnostic procedures reveal that 60% of patients have slight expression of CD34 (vascular origin), 21% have spinal muscular atrophy (epithelial and/or glandular origin), and 8% reveal desmin (muscular origin)." (PMID 21878118, 2011).
spindle cell liposarcoma (2 papers, 2015 to 2025). A morphologic variant of well differentiated liposarcoma characterized by the presence of bland spindle cells and lipoblasts within a myxoid or fibrous stroma. "Thorough pathologic evaluation is required for a definitive diagnosis of spindle cell liposarcoma, including the characteristic CD34 and MDM2 expression." (PMID 41141132, 2025).
splenic hemangioma (2 papers, 2014 to 2018). A hemangioma arising from the spleen. "This staining pattern also differentiates them from splenic hemangiomas, which contain CD8– and CD34+ endothelial cells." (PMID 24906658, 2014).
Stargardt disease (2 papers, 2020 to 2023). "The objective of the present study was to evaluate the safety and therapeutic potential of intravitreal use of a bone marrow mononuclear fraction containing CD34+ (BMMF) in ten patients with Stargardt macular dystrophy." (PMID 33488737, 2020). "On the basis of the results obtained, we conclude that autologous BMMF containing CD34+ cells proved to be safe for IV application to patients with Stargardt macular dystrophy during the study period, supporting the results of previous studies using the same cells for other ocular diseases." (PMID 33488737, 2020).
Telangiectasia (2 papers, 2024 to 2025). Telangiectasias refer to small dilated blood vessels located near the surface of the skin or mucous membranes, measuring between 0.5 and 1 millimeter in diameter. "Histologic parameters with worst inter-rater consistency were pathology on CD34 staining, mean epidermal thickness, eccrine gland loss, and telangiectasia." (PMID 40217251, 2025). "Parameters with the worst agreement were pathology on CD34 staining, mean epidermal thickness, eccrine gland loss, and telangiectasia." (PMID 39483897, 2024).
uterine sarcoma (2 papers, 2023 to 2024). "Both histomorphologic manifestations and IHC staining of CD34 overlap with COL1A1–PDGFB fusion uterine sarcomas." (PMID 36994196, 2023). "The presence of CD34 and/or S100 positivity on immunohistochemistry in a uterine sarcoma of the lower uterine segment or the cervix should trigger further NTRK testing, as an NTRK fusion may provide targeted therapeutic options with a potential positive impact on patient survival." (PMID 38151535, 2024). "IHC markers could be critical clues for diagnosis; usually, TRK, S100, and CD34 were stained positive, with markers of smooth muscle (desmin and caldesmon) and hormone receptors (ER and PR) stained negative for NTRK fusion uterine sarcoma." (PMID 36994196, 2023).
acute myelomonocytic leukemia (1 paper, 2017). "CD34 expression was negative in two cases, both of which were subtyped as likely acute myelomonocytic leukemia." (PMID 28620611, 2017).
adenosarcoma (1 paper, 2020). A low grade malignant neoplasm characterized by the presence of a benign epithelial component (tubular and cleft-like glands) and a low grade sarcomatous component that contains varying amounts of fibrous and smooth muscle tissues. "Other markers for adenosarcomas are SMA (50–68%), desmin (32–62.5%), CD34 (35%), and cytokeratin (25–27%)." (PMID 32972432, 2020).
age (1 paper, 2022). A temporal measurement of the time period elapsed since an identifiable point in the life cycle of an organism. "A low CD34+HSPC count in PB has been associated with cardiovascular morbidity and mortality, cardiopulmonary syndromes, and age‐associated diseases." (PMID 35166014, 2022).
age-related macular degeneration (1 paper, 2019). Age-related loss of vision in the central portion of the retina (macula), secondary to retinal degeneration. "The intravitreal use of CD34 + BMMSCs in patients with age-related macular degeneration has been evaluated in three phase I clinical trials, with improved visual acuity over a 12-month follow-up (NCT01518127, NCT01068561, and NCT01518842)." (PMID 30918717, 2019).
agranulocytosis (1 paper, 2015). "Moreover, lithium salts can not only increase the level of CD34 but also induce granulocyte colony-stimulating factor and increase the number of neutrophils by stimulating bone marrow; thus, it is a good choice in patients with leucopenia or agranulocytosis." (PMID 26576153, 2015).
ameloblastoma (1 paper, 2014). The most common odontogenic tumor, arising from the epithelial component of the embryonic tooth and usually affecting the molar-ramus region of the mandible or maxilla. "In the present study, the MVDs with the two CD105 and CD34 markers were significantly higher in ameloblastoma compared to OKC." (PMID 25469359, 2014). "In the present study, MVD, in terms of CD105 marker in ameloblastomas, was less than that in terms of CD34 marker." (PMID 25469359, 2014). "Materials and Method: In this descriptive-analytic cross-sectional study, 40 cases, comprising 10 odontogenic keratocysts and 30 ameloblastomas (10 plexiform, 10 follicular, and 10 unicystic type) were selected and were stained immuno-histochemically with CD34 and CD105." (PMID 25469359, 2014). "MVD with CD34 was significantly higher than MVD with CD105 in ameloblastomas (p= 0.00)." (PMID 25469359, 2014). "Wilcoxon test revealed significant differences in MVD verified by CD34 and CD105 markers in these lesions (p= 0.00), with higher vascular staining in ameloblastoma with CD34 compared to ameloblastoma with CD105 marker." (PMID 25469359, 2014). "In the current study, there were significant differences in MVD(considering CD34 marker) only between the plexiform and unicystic ameloblastomas; however, CD105 marker did not reveal any significant differences between them." (PMID 25469359, 2014).
anaphylaxis (1 paper, 2012). An acute hypersensitivity reaction that occurs from exposure to an allergen. "In our study, we provide the first analysis of four immune molecules (IL7Rα, L-selectin, CD34, CD103) in the PIA model, to determine the effect of altered adaptive responses and cell migration on food-induced anaphylaxis." (PMID 22935073, 2012).
and Lymphocytic Vasculitis (1 paper, 2021). "In the heterogeneous group of lymphocytic vasculitis, CD34+SCs/TCs are present around the perivascular mixed inflammatory infiltrate." (PMID 34298962, 2021).
angiolipoma (1 paper, 2020). A lipoma with prominent vascularity. "Numerous TCs/CD34+SCs are observed in the interstitium between vessels, adipocytes and myocytes in infiltrating the angiolipoma of muscle." (PMID 33353193, 2020).
Angiosarcoma of the bone (1 paper, 2024). "Angiosarcoma of the bone is also immunopositive for vascular endothelial markers such as CD31, CD34, von Willebrand factor (vWf), and factor VIII-related antigen." (PMID 39463621, 2024).
aortic stenosis (1 paper, 2012). Aortic valve stenosis is a aortic valve disease caused by the incomplete opening of the aortic valve. "Our results show a lower basal number of CD34+/CD144+ cells in the pre-surgical blood of patients who underwent CABG surgery compared to aortic stenosis valvular replacement patients." (PMID 22214418, 2012). "We aimed to assess the basal number of CD34+/KDR+ and CD34+/CD144+ cells in CABG patients, compared to aortic stenosis valvular replacement patients." (PMID 22214418, 2012). "In order to explore whether the different numbers of CD34+/CD144+ may be mediated by different clinical and analytical parameters between CABG and aortic stenosis valvular patients, intragroup analysis using these parameters were made." (PMID 22214418, 2012). "Panel A, CABG and aortic stenosis valvular patients did not possess a significantly different level of CD34+/KDR+ cells, although a decreasing trend was noted for CABG." (PMID 22214418, 2012).
artery disease (1 paper, 2021). "We identified low CD34 level in the advanced phases of artery disease compared to the study subjects with moderate PAD and no PAD at all who demonstrated CD34 level higher by 30%." (PMID 34679610, 2021).
atrial septal defect (1 paper, 2022). Interauricular communication is a congenital malformation characterized by a communication between the atrial chambers of the heart. "In this study, the surface of the occluder membrane was coated with sericin/CD34 antibodies to promote the growth of endothelial cells and the regeneration of defective tissue and enhance the repair of the atrial septal defect." (PMID 36616459, 2022).
autoimmune glomerulonephritis (1 paper, 2017). An autoimmune form of glomerulonephritis (disease). "Yaa mice developed severe autoimmune glomerulonephritis, and the number of CD34+ glomerular capillaries decreased significantly in GLs compared to that in control mice." (PMID 28870174, 2017).
Azoospermia (1 paper, 2021). Absence of any measurable level of sperm,whereby spermatozoa cannot be observed even after centrifugation of the semen pellet. "However, no studies have been published to treat azoospermia with the help of MSCs except an abstract from Jordan scientists demonstrating therapeutic effects of intratesticular injections of CD34/CD133 BM-MSCs in azoospermia men." (PMID 33823925, 2021).
Barth syndrome (1 paper, 2025). Barth syndrome (BTHS) is an inborn error of phospholipid metabolism characterized by dilated cardiomyopathy (DCM), skeletal myopathy, neutropenia, growth delay and organic aciduria. "We used this system to compare neutrophil differentiation from CD34+ progenitors of healthy control (HC) and BTHS patients, recruited from the NHS National Barth Syndrome Service at Bristol Royal Hospital for Children." (PMID 39962231, 2025).
basosquamous carcinoma (1 paper, 2026). A basal cell carcinoma which displays squamous differentiation. "In all samples of human basosquamous carcinomas, within the tumor mass and between the tumor nests, there was abundant tumor stroma of a reactive–proplastic type with relatively numerous large fibroblast-like cells that were CD34 negative." (PMID 41597444, 2026).
benign breast disease (1 paper, 2016). "There was no major difference in the level of CD34+ VEGFR2+ EPCs between malignant and benign breast disease patients." (PMID 27881867, 2016).
benign gastrointestinal neoplasms (1 paper, 2025). "Other neoplastic lesions requiring differentiation include inflammatory fibroid polyp, benign gastrointestinal neoplasms associated with PDGFRA mutations and identified by CD34(+) and CD117(−) IHC profiles." (PMID 41262926, 2025).
benign soft tissue tumors (1 paper, 2023). "With regard to diagnosis, CD34 marker in IHC investigation of samples by sensitivity of more than 85% has a key role in differentiating DFSP from other benign soft tissue tumors." (PMID 36653860, 2023).
blast crisis (1 paper, 2015). "To this end, we isolated CD34+ cells from the peripheral blood of a patient diagnosed with blast crisis CML (BC CML) and plated them in stromal co-cultures." (PMID 26016997, 2015).
blood vessel tumors (1 paper, 2024). "The cover was formed of endothelial cells, which were CD34 positive in blood vessel tumors and D2-40 positive in lymphatic vessel tumors." (PMID 38397861, 2024).
bone metastasis (1 paper, 2022). Transfer of a neoplasm from its primary site to bones. "In the current analyses, CSPG4 was positively associated with CD34 and HIF1A, together with the previous report on the role of CSPG4 in angiogenesis, CSPG4 tends to be a promising molecule to be evaluated for its involvement in bone metastasis related angiogenesis." (PMID 35685372, 2022).
Bowen's disease (1 paper, 2025). "SCC-C, often associated with Bowen's disease, also features clear cells but lacks the trichilemmal keratinization and glycogen content seen in TC; moreover, it does not show immunohistochemical evidence of trichilemmal differentiation (e.g., CD34)." (PMID 40308391, 2025).
Branchioma (1 paper, 2023). A tumor derived from branchial epithelium or branchial rests. "Moreover, our case adds to the morphological (prominent neuroendocrine-like nested/organoid features) and immunophenotypic (CD34 expression combined with RB1 loss) heterogeneity/pitfalls related to the differential diagnosis of branchioma." (PMID 37401932, 2023).
bronchiectasis (1 paper, 2022). Segmental, irreversible dilation of the bronchial tree resulting in the accumulation of secretions which leads to obstruction. "She had a CD34 + top-up at 14 years post-HSCT for poor B cell recovery and absent myeloid engraftment associated with recurrent LRTI and bronchiectasis despite adequate IRT." (PMID 35579633, 2022).
cerebral edema (1 paper, 2024). "Overall, these results may suggest that either low neuroinflammation or increased acute levels of CD34+ BMPCs/EPCs, or both, protects BBB-forming endothelial cells and reduces cerebral edema." (PMID 38397735, 2024).
chorioamnionitis (1 paper, 2019). A morphologic finding indicating inflammation of the fetal sac membranes. "Absolute number of CD34+ cells/kg was decreased with extremely low birthweight (ELBW), prolonged rupture of membranes, and chorioamnionitis." (PMID 31799226, 2019).
colonic adenomas (1 paper, 2009). "The endothelium associated with colonic adenomas and adenocarcinomas (i.e., within two low-power fields of the tumour cells) was positive for Dll4 in 60–100% of vessels (identified by CD34 immunoreactivity in serial sections, data not shown)." (PMID 19844231, 2009).
congenital sideroblastic anaemia (1 paper, 2015). "Therefore, we prepared CD34+ BM cells from four SF3B1-mutated MDS-RS patients (MDS1, TP1; MDS2, TP1; MDS3; MDS4) and one congenital sideroblastic anaemia patient (MDS5 with ALAS1 mutation), which was used as a control." (PMID 26643973, 2015).
coronary artery calcification (1 paper, 2009). Calcification of the coronary artery, used as a measure of coronary atherosclerosis, a risk factor for myocardial infarction. "CD34+ cell count by fluorescence-activated cell sorting, coronary artery calcification (CAC) by electron beam computed tomography, and CVD risk factors were obtained." (PMID 20407620, 2009).
Currarino syndrome (1 paper, 2012). "MNX1 gene is involved in a congenital malformation, the Currarino syndrome (congenital malformation) and also previously reported in CD34+ cells, B cells and B lymphoid tissues." (PMID 22980038, 2012).
Cutaneous leiomyoma (1 paper, 2025). The presence of leiomyoma of the skin. "Focal positivity for CD34 and cytokeratin AE1/AE3, also present in our case, is rare but has been documented in cutaneous leiomyomas." (PMID 40851728, 2025).
cylindroma (1 paper, 2016). "Some genes, such as CD34, that have been described as MYB target genes in ACC 4 were, however, found to be underexpressed in cylindroma (fold change decrease = ×0.47), whilst genes such as MAD1L1 were not differentially expressed between tumours and controls (data not shown)." (PMID 26969893, 2016).
deficiency anemia (1 paper, 2015). "The percentage of total CD34+ cells and %CD34+/CD117+/CD13+ cells (myeloid blasts) were increased in only one case of deficiency anemia, associated with a shift to the left in the granulopoiesis." (PMID 25924846, 2015).
dermal tumor (1 paper, 2021). "In our study, two cases (IFS and fibrohistiocytic dermal tumor) were S100 and CD34 negative." (PMID 32860002, 2021).
diabetic neuropathy (1 paper, 2023). A chronic, pathological complication associated with diabetes mellitus, where nerve damages are incurred due to diabetic microvascular injury involving small blood vessels that supply these nerves, resulting in peripheral and/or autonomic nerve dysfunction. "In light of these results, it seems that the CD31 antigen may be the most promising marker to confirm the association between BV increase and diabetic neuropathy at short evolution (less than 15 years) and the CD34 antigen at long evolution." (PMID 38054043, 2023).
dilatation (1 paper, 2025). "Importantly, longitudinal and transverse ultrasound images taken four weeks after Ang II induction revealed more pronounced aortic dilatation in CD34+ cell‐deleted mice, and color Doppler ultrasound revealed aggravated false channel and intramural hematoma." (PMID 39731355, 2025).
embryonal carcinoma (1 paper, 2016). A non-seminomatous malignant germ cell tumor characterized by the presence of large germ cells with abundant cytoplasm resembling epithelial cells, geographic necrosis, high mitotic activity, and pseudoglandular and pseudopapillary structures formation. "For instance, one of the three CD34+ hematopoietic stem cell-derived clones reprogrammed with the OKS lentiviral vector produced tumors with high malignant content, consisting of embryonal carcinoma and yolk sac tumor." (PMID 26880963, 2016).
embryonal sarcoma (1 paper, 2022). "UESLs are usually diffusely positive for vimentin and a1-antitrypsin and focally positive for cytokeratin, desmin, α-SMA, muscle-specific actin, CD68, myoglobin, neuron-specific enolase, S100, and CD34, suggesting that an embryonal sarcoma is undifferentiated." (PMID 36107353, 2022).
erectile dysfunction (1 paper, 2018). Persistent or recurrent inability to achieve or to maintain an erection during sexual activity. "The number of circulating CD34+CD133+ EPCs is significantly reduced in patients with erectile dysfunction without known cardiovascular risk factors." (PMID 30581475, 2018). "Furthermore, as erectile dysfunction is also a complication of overweight and type-1 DM, the number of CD34+VEGFR-2+ EPCs has been found to be correlated with the severity of erectile dysfunction." (PMID 30581475, 2018).